ESX1 (ESX homeobox 1)
Description:
May coordinately regulate cell cycle progression and transcription during spermatogenesis. Inhibits degradation of polyubiquitinated cyclin A and cyclin B1 and thereby arrests the cell cycle at early M phase. ESXR1-N acts as a transcriptional repressor. Binds to the sequence 5'-TAATGTTATTA-3' which is present within the first intron of the KRAS gene and inhibits its expression. ESXR1-C has the ability to inhibit cyclin turnover.
Synonyms: ESX1L; ESXR1
Tractability: No criterion of Open Targets' tractability assessment is met for any kind of drug.
Gene: Protein-coding gene on chromosome X (104,250,038 to 104,254,933, reverse strand). Ensembl gene ENSG00000123576.
Subcellular location: Cytoplasm; Nucleus
Subcellular location (Human Protein Atlas): Nuclear speckles
Gene Ontology:
Molecular function: DNA-binding transcription repressor activity, RNA polymerase II-specific; RNA polymerase II transcription regulatory region sequence-specific DNA binding; sequence-specific DNA binding; sequence-specific double-stranded DNA binding; DNA-binding transcription factor activity, RNA polymerase II-specific; DNA binding
Biological process: negative regulation of DNA-templated transcription; negative regulation of transcription by RNA polymerase II; regulation of cell cycle; neuron development; regulation of transcription by RNA polymerase II; regulation of DNA-templated transcription
Cellular component: cytoplasm; nuclear speck; nucleus; chromatin
Homologues: Orthologues: chimpanzee ESX1 (82% identical), macaque ESX1 (75% identical), dog ESX1 (33% identical), mouse Esx1 (26% identical), rat AABR07040695.1 (23% identical). Paralogues in human: ARX (18% identical), PROP1 (17% identical), RAX (17% identical), UNCX (16% identical), OTP (16% identical), PAX6 (15% identical), SHOX2 (15% identical), MIXL1 (15% identical), SHOX (15% identical), ALX4 (15% identical), PAX3 (15% identical), PAX7 (14% identical), and 38 more.
Diseases named in the same sentence as ESX1 in open-access papers:
ESX1 is named in the same sentence as 22 diseases in open-access papers, as found by Europe PMC text mining. Sharing a sentence is not in itself a finding about the gene and the disease. The quoted sentences say what the papers report.
tuberculosis (15 papers, 2010 to 2026). A chronic, recurrent infection caused by the bacterium Mycobacterium tuberculosis. "Pathogenic mycobacteria, which are responsible for tuberculosis and other long-term diseases, use the ESX-1 system to transport proteins that control the host response to infection and promote bacterial survival." (PMID 38445877, 2024). "Here, we study the function of ESX-1 accessory proteins EccA1, EspG1 and EspH in ESX-1 secretion in Mycobacterium marium, the causative agent of fish tuberculosis." (PMID 30102741, 2018). "In tuberculosis-causing mycobacteria, the ESX-1 secretion system is known to be a key virulence determinant, with its absence causing severe attenuation, as seen in the ESX-1-deleted vaccine strains Mycobacterium bovis bacillus Calmette-Guérin (BCG) and Mycobacterium microti MP Prague." (PMID 34006663, 2021). "We show that Mycobacterium marinum, an animal pathogen and model for studying ESX-1 and tuberculosis, switches which ESX-1 proteins are secreted in response to acidic pH, an infection relevant signal." (PMID 42053305, 2026). "Mycobacterium tuberculosis, the causative agent of human tuberculosis, and Mycobacterium marinum, a poikilothermic fish pathogen, share a conserved (ESAT-6) secretion system [ESAT-6 system 1 (ESX-1)] that is required for pathogenesis (3, –, 5)." (PMID 38445877, 2024). "Taken together with our results, it is now apparent that despite the similarities in the secreted WXG proteins EsxA and EsxB, a clear difference between ESX-1 involvement in HGT in M. smegmatis and tuberculosis-causing mycobacteria exists." (PMID 34006663, 2021). "An espG1 deletion broadly aborts ESX-1 secretion and thus resulted in severe attenuation in a zebrafish model for tuberculosis, whereas EccA1 is only crucial under specific growth conditions." (PMID 30102741, 2018). "M. marinum established local infection in mouse tails, with Esx-1-dependent formation of caseating granulomas similar to those formed in human tuberculosis, and bone deterioration reminiscent of skeletal tuberculosis." (PMID 20463815, 2010). "Possibly Esx-1 has evolved to increase the inflammatory response in order to promote bacterial spread to new hosts, as when granulomas rupture into bronchi during tuberculosis, or into the skin during piscine infection by M. marinum." (PMID 20463815, 2010). "ESX-1 secretes the potent antigens ESAT-6 (EsxA) and CFP-10 (EsxB), as well EspA and EspC, to cause phagosome dysfunction permitting dissemination of M. tuberculosis from the phagosome to the cytoplasm and is therefore a major factor in tuberculosis pathogenesis." (PMID 29273788, 2017). "Thus, Mtb ESX1-mediated fractalkine production results in enhanced recruitment of CD11b+ monocytic cells, the niche for the tubercle bacillus, but not in CD3+ T cells, many subtypes of which are implicated in protection against tuberculosis." (PMID 24631198, 2014). "A number of virulence mechanisms have been attributed to ESX1 including phagosomal maturation arrest, cytosolic bacterial translocation and host cell necrosis in cells 72 h post-infection, although it is unknown which of these is the most important in human tuberculosis in vivo." (PMID 24631198, 2014). "The presence of ESAT-6 and CFP 10 proteins, which are the most immunogenic proteins of the Esx-1 system and have been widely investigated for the immunodiagnosis of tuberculosis, in some Mycobacteriaceae and in Mycobacterium leprae, poses limitations for their use in specific diagnoses of TB." (PMID 38930534, 2024).
Granuloma (6 papers, 2010 to 2025). A compact, organized collection of mature mononuclear phagocytes, which may be but is not necessarily accompanied by accessory features such as necrosis. "Granuloma necrosis, a key pathogenic event, is heavily impacted by the ESX-1 secretion system, as extensively reported in the literature." (PMID 40134379, 2025). "WhiB6 is able to regulate the expression of ESX-1 during mycobacterial dissemination and granuloma formation in zebrafish embryo model." (PMID 31117936, 2019). "We speculate that ESX-1-mediated and neutrophil-dependent immunopathology may promote the caveation of granulomas and thus bacterial transmission to new hosts." (PMID 37017530, 2023). "Here, we find that ESX-1 promotes the production of CXCL1, 2, and 5 and the accumulation of neutrophils in granuloma core regions." (PMID 37017530, 2023). "marinum were smaller, did not develop into well-delineated granulomas during the timeframe of the infection, and did not exhibit central necrosis until 28 days post infection (not shown), indicating that Esx-1 is required for a normal granulomatous response." (PMID 20463815, 2010).
Azoospermia (2 papers, 2021 to 2023). Absence of any measurable level of sperm,whereby spermatozoa cannot be observed even after centrifugation of the semen pellet. "The familial segregation analysis of ESX1 variants is of good value in confirming the relationship between ESX1 mutation and azoospermia, yet we lost touch with the patients who were enrolled in this study more than ten years ago." (PMID 33633269, 2021). "However, it is worth highlighting the results obtained in the male gonad tissues from a patient with azoospermia with a detected mutation in the ESX1 gene, where we noted an inverse correlation." (PMID 37783880, 2023).
male infertility (2 papers, 2021 to 2023). The inability of the male to effect fertilization of an ovum after a specified period of unprotected intercourse. "Nevertheless, more studies are still needed to thoroughly investigate the role of ESX1 in male infertility." (PMID 33633269, 2021).
astrocytoma (1 paper, 2019). "Though recurrent somatic mutations in IMSCTs were rare, we identified NF2 mutations in 15.7% of tumors (ependymoma, N = 7; astrocytoma, N = 1), RP1 mutations in 5.9% of tumors (ependymoma, N = 3), and ESX1 mutations in 5.9% of tumors (ependymoma, N = 3)." (PMID 31822682, 2019).
ependymoma (1 paper, 2019). A WHO grade II, slow growing tumor of children and young adults, usually located intraventricularly. "With missense RP1 mutations observed in two classic ependymomas and one myxopapillary ependymoma and missense ESX1 mutations observed in one classic ependymoma, one myxopapillary ependymoma, and one subependymoma." (PMID 31822682, 2019). "The other two recurrently mutated genes in our IMSCT cohort, RP1 and ESX1, were observed in ependymomas as well." (PMID 31822682, 2019).
glioma (1 paper, 2017). A benign or malignant brain and spinal cord tumor that arises from glial cells (astrocytes, oligodendrocytes, ependymal cells). "ESX1 had been previously reported to be a driver of neoplastic processes involving lower grade gliomas." (PMID 28388591, 2017).
pulmonary TB (1 paper, 2017). "A plausible explanation for the poor protection of BCG against pulmonary TB is the loss of several genomic regions, including RD1 (refs 5, 8), which encodes ESAT6, CFP10 and part of their secretory machinery contained in the ESX-1 secretion system." (PMID 28706226, 2017).
testicular seminoma (1 paper, 2023). A malignant germ cell tumor arising from the testis. "The aim of this study was to activate the ESX1 gene using CRISPRa technology in human germ cells (testicular seminoma cells—TCam-2)." (PMID 37783880, 2023).
infection (91 papers, 2009 to 2026). The state of being infected such as from the introduction of a foreign agent such as serum, vaccine, antigenic substance or organism. "Several components of the ESX-1 secretion have been implicated in the formation of the granuloma during infection." (PMID 40304497, 2025). "Overall, this study further defined the regulatory network underlying control of the ESX-1 secretion system and demonstrated its importance during infection." (PMID 38445877, 2024). "The loss of ESX-1 secretion led to reduced IFN induction during macrophage infection with the ΔdrrC strain, as compared to the WT and complemented strains." (PMID 38661343, 2024). "The deletion of ESX-1 substrate genes attenuates pathogenic mycobacteria in infection models (4, 25, –, 28)." (PMID 38445877, 2024). "EsxA is part of the virulence-associated ESAT-6 secretion system ESX-1 and is highly attenuated in a murine model of infection." (PMID 35844560, 2022). "It achieved nearly wild-type bacterial burdens during zebrafish larval infection (0.82 ± 0.16 fold of wild type vs. 0.29 ± 0.05 fold for Mm−ΔRD1), and this was associated with wild type levels of granuloma formation, an ESX-1–mediated phenotype." (PMID 35271388, 2022). "Upon infection, Mtb is phagocytosed by macrophages and uses its virulence-associated ESX-1 secretion system to modulate the host cell." (PMID 34225486, 2021). "Successful infection requires the secretion of virulence factors, and the proteins secreted by the ESX-1 secretion system are vital for the virulence and pathogenicity of mycobacteria." (PMID 33290182, 2021). "The attenuation of the ESX-1-deficient strain initially increases but then levels off with a spread of (esx-1/WT) ratios by 14 days post-infection." (PMID 33228849, 2020). "This punctate distribution was less pronounced during infection with the ΔesxA mutant, revealing that M. tuberculosis, in an ESX-1-dependent manner, causes widespread endomembrane damage or otherwise manipulates ESCRT-III localization." (PMID 30482832, 2018). "Polyubiquitination of the NOD2-effector RIP2 was significantly diminished upon infection with ESX-1-deficient M. tuberculosis when compared to wild-type bacteria, identifying RIP2 as a major downstream effector of NOD2 in the recognition of M. tuberculosis." (PMID 29230217, 2017). "Together, these data demonstrate that the EsxAMT variants promoted Esx-1-exporter activity in an ex vivo cell-based infection model." (PMID 27625110, 2016). "Previous analyses have suggested that secretion of TNFα is unaffected or even decreased during macrophage infection with wild type compared to Esx-1-deficient mycobacteria." (PMID 20463815, 2010). "As in mammalian models of infection with M. tuberculosis, loss of the ESX-1 secretion system greatly attenuates the virulence of Mm in its natural fish and amphibian hosts." (PMID 19436699, 2009). "Indeed, ESX-1-deficient M. marinum strains have reduced macrophage recruitment and aggregation of macrophages in zebrafish larvae at 5 days post-infection." (PMID 40304497, 2025). "The finding that in mTOR deficiency, infection with very few ESX-1/ESAT-6-expressing mycobacteria, likely confined to a single phagosome/phagolysosome, causes global loss of mitochondrial membrane potential suggests that there is rapid propagation of the initial localized damage." (PMID 36103894, 2022). "Snapshots from live-cell imaging in deficient surfactant (DS) conditions at 4 days post-infection for (A) wild-type Mtb, (B) an attenuated ESX-1-deficient strain (esx-1), and (C) at 6 days post-infection for the avirulent Δicl1Δicl2 strain infected at a higher inoculum." (PMID 33228849, 2020). "The type VII secretion system ESX1 system has also been implicated in cellular necrosis leading to increased cellular egress later in infection and fractalkine could represent an early stage recruiting permissive cells prior to their release by necrosis." (PMID 24631198, 2014).
infection (continued). "The ESX-1 secretion system causes the induction of host cell death upon infection in macrophages." (PMID 22911706, 2012). "However, by 28 days post infection vertebrae from both ΔRD1 and wild type infections showed similarly reduced bone volume, suggesting that infection with Esx-1-deficient bacteria does induce bone erosion, but with delayed kinetics." (PMID 20463815, 2010). "Consequently, the avirulent phenotype of ESX-1-deficient mycobacteria might be partly attributable to the inability to secrete EspA and/or EspC early in infection." (PMID 30673778, 2019). "Thus, this may be a pathogenic role for the Esx-1 secretion system during infection, and might explain the requirement for Esx-1 in activation of the inflammasome, which generally responds to cytoplasmic signals." (PMID 20463815, 2010). "During early infection, the ESX-1 system is particularly important for the early granuloma stages that allow for later progression into the mature structure." (PMID 40304497, 2025). "Where the ESX-1 system is crucial for mycobacterial survival in early infection, ESX-5 secretion establishes a moderate, persistent infection." (PMID 40304497, 2025). "Our in vivo data demonstrating increased IL-23 production by dendritic cells in ESX-1 mutant infections is consistent with the old observation that ESX-1 suppresses IL-12 p40 in vitro." (PMID 40463021, 2025). "Together, these data demonstrate a critical role for EspN and the ESX-1 transcriptional network during infection." (PMID 38445877, 2024). "Our data propose a model where EspM and EspN counterbalance to regulate ESX-1 gene transcription both in the laboratory and during infection." (PMID 38445877, 2024). "For the first time, we have identified an infection-dependent transcriptional activator responsible for regulating both the ESX-1 components and substrates." (PMID 38445877, 2024). "Here, we discovered and characterized EspN, a transcriptional regulator of the ESX-1 system that is essential for infection." (PMID 38445877, 2024). "Our findings suggest that EspN is required for ESX-1 function during infection possibly due to transcriptional regulation of ESX-1 genes." (PMID 38445877, 2024). "EspN is also independently required for M. marinum growth within and cytolysis of macrophages, similar to the ESX-1 genes, and for disease burden in a zebrafish larval model of infection." (PMID 38445877, 2024). "EccCa1 gene which downstream of MIRU39 is part of the ESX-1 specialized secretion system, which delivers several virulence factors to host cells during infection, including the key virulence factors ESAT-6 and CFP-10." (PMID 36646991, 2023). "To confirm the specific effect of chromosome 3 GBPs on ESX1 mutants in the setting of intact immunity, we conducted a competitive infection of wild type and Gbpchr3−/− mice with an equivalent number of H37Rv and Δeccb1 bacteria." (PMID 36769182, 2023). "We reasoned that if acetylation of EsxA was required for ESX-1 function then the Δemp1 M. marinum strain would phenocopy the ΔeccCb1 strain during macrophage infection." (PMID 37772840, 2023). "The number of infected CD64+ cells also largely correlated with their influx into the tissue, and ESX-1 had only a minor effect on the relative infection rate of these cells." (PMID 37017530, 2023). "We demonstrated that Emp1 is dispensable for ESX-1-dependent secretion and hemolysis and for growth in macrophages during infection." (PMID 37772840, 2023). "We tested ESX-1 function and mycobacterial virulence using in vitro systems and a macrophage model of infection." (PMID 37772840, 2023). "To conclude, this study establishes that phosphorylation plays an essential role in regulating Esx-1-mediated activity post infection and is crucial for the intracellular survival of the pathogen." (PMID 37791794, 2023).